CAMK1G (calcium/calmodulin dependent protein kinase IG)
Description:
Calcium/calmodulin-dependent protein kinase belonging to a proposed calcium-triggered signaling cascade. In vitro phosphorylates transcription factor CREB1 (By similarity).
Synonyms: CLICK3; VWS1; CLICKIII; dJ272L16.1
Tractability: Small molecule: a structure with a bound ligand is known; a high-quality ligand is known; it belongs to a druggable protein family. Antibody: UniProt places it where antibodies can reach, with medium confidence; its Gene Ontology location is reachable by antibodies, with medium confidence. PROTAC: its protein half-life has been measured; a small molecule that binds it is known.
Target class: Protein Kinase; CAMK protein kinase group; Enzyme; CAMK protein kinase CAMK1 family; Kinase
Gene: Protein-coding gene on chromosome 1 (209,583,714 to 209,613,939, forward strand). Ensembl gene ENSG00000008118.
Subcellular location: Cytoplasm; Golgi apparatus membrane; Cell membrane
Subcellular location (Human Protein Atlas): Cytosol; Nucleoplasm; Basal body; Primary cilium
Gene Ontology:
Molecular function: protein binding; calcium/calmodulin-dependent protein kinase activity; calmodulin binding; ATP binding; protein kinase activity; protein serine kinase activity
Biological process: signal transduction
Cellular component: cytoplasm; calcium- and calmodulin-dependent protein kinase complex; endomembrane system; Golgi membrane; plasma membrane
Genetic constraint (gnomAD): Loss-of-function variants: 24 observed, 54.68 expected, observed/expected ratio (o/e) 0.44, 90% interval 0.32 to 0.62. The upper end of that interval is the gene's LOEUF score, 0.62, which puts it in group 2 of 6, group 1 being the genes least tolerant of losing a copy. Missense variants: 505 observed, 611.25 expected, observed/expected ratio (o/e) 0.83, 90% interval 0.77 to 0.89. Synonymous variants: 236 observed, 235.05 expected, observed/expected ratio (o/e) 1, 90% interval 0.9 to 1.12.
Homologues: Orthologues: chimpanzee CAMK1G (99% identical), macaque CAMK1G (99% identical), dog CAMK1G (94% identical), rat Camk1g (93% identical), mouse Camk1g (92% identical), guinea pig CAMK1G (90% identical), pig CAMK1G (87% identical), rabbit CAMK1G (85% identical), tropical clawed frog camk1g (68% identical), zebrafish camk1gb (57% identical), zebrafish camk1ga (52% identical). Paralogues in human: CAMK1D (53% identical), CAMK1 (48% identical), PNCK (42% identical), CAMKV (33% identical), CAMK2D (30% identical), CAMK2A (30% identical), CAMK2B (30% identical), CAMK2G (30% identical), PSKH1 (29% identical), DCLK1 (28% identical), DCLK2 (28% identical), PSKH2 (27% identical), and 10 more.
Diseases named in the same sentence as CAMK1G in open-access papers:
CAMK1G is named in the same sentence as 10 diseases in open-access papers, as found by Europe PMC text mining. Sharing a sentence is not in itself a finding about the gene and the disease. The quoted sentences say what the papers report.
Anxiety (2 papers, 2022 to 2024). Intense feelings of nervousness, tension, or panic often arise in response to interpersonal stresses. "Camk1g is a neuron-specific glucocorticoid-regulated transcription factor whose activity in the amygdala underlies anxiety-related and fear conditioning behavior." (PMID 38389788, 2024). "Mice with bilateral amygdala-specific Camk1g knock-down showed increased anxiety-like behaviors in the light-dark box, and an increase in freezing behavior after fear-conditioning, but normal spatial working memory during exploration of a Y-maze." (PMID 36293185, 2022). "Here, we have assessed the behavior of CeA Camk1g knockdown (CeA-Camk1g-KD) mice in a series of tests that measure stress-induced memory formation and expression as well as anxiety-like behavior and working memory." (PMID 36293185, 2022). "Next, the effect of Camk1g knockdown in the mouse amygdala on anxiety-related phenotypes was studied." (PMID 36293185, 2022). "Thus, we confirm that Camk1g is a neuron-specific GR-regulated transcript, and show that it is specifically involved in behaviors related to anxiety, as well as responses conditioned by aversive stimuli." (PMID 36293185, 2022). "Camk1g knockdown animals presented higher anxiety in this test." (PMID 36293185, 2022).
hyperaldosteronism (1 paper, 2021). Overproduction of aldosterone by the adrenal glands, which may lead to hypokalemia and/or hypernatremia. "Camk1g at Fmgq1 is a member of this pathway and people with obesity often experience hyperaldosteronism." (PMID 33723359, 2021).
memory impairment (1 paper, 2017). "It is very likely that Camk1g, which has not been reported before in relation to memory impairment, may function in a similar manner." (PMID 29066959, 2017).
osteosarcoma (1 paper, 2024). A usually aggressive malignant bone-forming mesenchymal neoplasm, predominantly affecting adolescents and young adults. "Although the roles of SP110, HHAT, MORC4, PAGE5, MAP7, and CAMK1G in osteosarcoma have rarely been reported, their involvement in other types of cancer has been revealed." (PMID 39980969, 2024).
prostate adenocarcinoma (1 paper, 2024). "CAMK1G has been identified as a significant predictor of favorable overall survival of patients with prostate adenocarcinoma." (PMID 39980969, 2024).
cancer (4 papers, 2020 to 2025). A tumor composed of atypical neoplastic, often pleomorphic cells that invade other tissues. "The CpG probe, cg20994118 (mapped to dark kinase gene, CAMK1G), was commonly hypomethylated in 12 cancers." (PMID 33801837, 2021). "CAMK1G has been shown to phosphorylate the transcription factor CREB1, which plays a key role in promoting cancer development and progression by enhancing cellular plasticity and driving metabolic reprogramming." (PMID 40832614, 2025). "The understudied multi-functional CaMKs (CAMK1D, CAMK1G, CAMKK1, PNCK) are overexpressed in 12 cancers, with PNCK being overexpressed in 9 alone." (PMID 33205077, 2020).
CAMK1G also shares sentences with these, for which no sentence is quoted: epilepsy (1 paper); Obesity (1); schizophrenia (1); tumor (1).